DPYD (dihydropyrimidine dehydrogenase)
Diseases named in the same sentence as DPYD in open-access papers (continued):
Sharing a sentence is not in itself a finding about the gene and the disease.
pancreatic cancer (8 papers, 2008 to 2026). "In the present study, we have demonstrated that the upregulation of DPYD expression in pancreatic cancer is associated with proliferation, invasiveness, and angiogenesis as well as resistance to 5‐FU treatment." (PMID 39158384, 2024). "In our previous paper, we reported that the expression of DPYD in human pancreatic cancer tissue arrays is a poor prognostic factor." (PMID 39158384, 2024). "The heightened expression of dihydropyrimidine dehydrogenase (DPYD) in pancreatic cancer not only accelerates pyrimidine degradation but also stimulates cell proliferation and invasiveness, accompanied by the upregulation of MMP9 and MEP1A." (PMID 39158384, 2024). "This was achieved by downregulation of the STAT3 dihydropyrimidine dehydrogenase (DPYD) pathway, which has a central importance in the development of pancreatic cancer." (PMID 35956766, 2022). "This analysis revealed an increase of CDA (P=0.003), DCK (P=0.06), DPYD (P=ns) and TP (P=0.01) in pancreatic cancer tissues, whereas hENT1 (P=ns) expression was slightly reduced compared with the normal pancreas." (PMID 18728667, 2008). "Enrichment analysis indicated DPYD involvement in pancreatic cancer and related diseases." (PMID 41832427, 2026). "A combination therapy comprising lutetolin, a DPYD inhibitor, and 5‐FU may be effective for treating pancreatic cancers." (PMID 39158384, 2024). "Other putative STAT3 targets were DPYD, a gene encoding a key 5-FU-metabolizing enzyme, MUC1, which impacts on the response to radiotherapy in pancreatic cancer, and HIF1A, an established target of JAK-STAT signaling and previously reported as potential determinant of tumor radiosensitivity." (PMID 33530306, 2021). "Another reason could be the weak expression of DPYD in KPPC mice with pancreatic cancer." (PMID 39158384, 2024). "Additionally, some studies suggest that DPYD expression contributes to the epithelial‐mesenchymal transition in high‐grade cancer cell lines, although its role in pancreatic cancer remains unclear." (PMID 39158384, 2024). "However, the detailed mechanism of how DPYD is involved in pancreatic cancer remains unclear." (PMID 39158384, 2024). "However, since we had not examined the effects of overexpression on pancreatic cancer cells or performed in vivo studies, we overexpressed DPYD in low‐DPYD‐expressing cells and investigated its impact on proliferation and invasiveness both in vitro and in vivo." (PMID 39158384, 2024).
mucositis (7 papers, 2014 to 2025). Mucositis is inflammation and damage of the mucous membranes lining the mouth and other parts of the gastrointestinal (GI) tract. "More specifically, we aimed to evaluate the association between DPYD mutational status and incidence of 5-FU-related adverse events, such as mucositis, as well as the associated consequences of dysphagia, pharyngolaryngeal pain, and aspiration pneumonia." (PMID 35200545, 2022). "Subgroup analysis according to retrospective and extended DPYD mutational status characterization, however, demonstrated a 58% increase in grade ≥3 mucositis for patients later shown to be carriers of selected mutant alleles." (PMID 35200545, 2022). "The chemotherapy was started several weeks back, but the patient was being monitored closely for features of mucositis due to a recently discovered dihydropyrimidine dehydrogenase (DPD) genotype." (PMID 40443641, 2025).
Hand-foot syndrome (6 papers, 2014 to 2025). "The majority (>85%) of administered 5-FU is degraded by the enzyme dihydropyrimidine dehydrogenase (DPD) in the liver, generating alpha-fluoro-beta-alanine (FBAL), a catabolite associated with off-target toxicities such as hand-foot syndrome." (PMID 40956795, 2025). "Most (> 85%) administered 5-FU is degraded by the enzyme dihydropyrimidine dehydrogenase (DPD) in the liver, generating alpha-fluoro-beta-alanine (FBAL), a catabolite associated with off-target toxicities such as hand-foot syndrome and cardiotoxicity." (PMID 37000221, 2023).
lung carcinoma (6 papers, 2013 to 2023). "In addition, proliferating cell nuclear antigen-normalized mRNA expression of DPYD has previously been reported to be associated with sensitivity to CDDP in lung cancer tissues." (PMID 23420099, 2013). "All three variants were detected in primary tumors of two patients (UH1 & UH2), specifically in the DPYD (dihydropyrimidine dehydrogenase), MCL1 (v-myc myelocytomatosis viral oncogene homolog 1, lung carcinoma derived [avian]), and TNK2 (tyrosine kinase, non-receptor, 2) genes." (PMID 25950952, 2015).
rectal cancer (6 papers, 2013 to 2023). A primary or metastatic malignant neoplasm that affects the rectum. "Similar results have been identified in advanced rectal cancer patients treated with fluoropyrimidine-based chemotherapy, suggesting that DPYD expression confers a more aggressive behavior in these tumors." (PMID 37372990, 2023). "Notably, Dihydropyrimidine dehydrogenase (DPYD) was the only metabolic gene identified in the unfavorable set, consistent with its biological function and previous reports of its predictive power in 5-FU treated rectal cancers." (PMID 29026541, 2017).
schizophrenia (6 papers, 2017 to 2025). A major psychotic disorder characterized by abnormalities in the perception or expression of reality. "There are 3 genes in the topological domain containing the associated SNPs of 1p21.3 locus (MIR137HG, MIR2682 and DPYD), which may be associated with schizophrenia and bipolar disorder." (PMID 34242216, 2021). "Similarly, DPYD, an enzyme involved in pyrimidine metabolism, has been associated with neurological phenotypes, suggesting that even modest antigenic similarities could contribute to immune-mediated mechanisms in schizophrenia." (PMID 41226360, 2025). "Most carriers of heterozygous DPYD mutations are healthy, but some patients with hemizygous deletions affecting DPYD have neurodevelopmental disorders, including autism spectrum disorders, schizophrenia, epilepsy, and intellectual disability." (PMID 28126037, 2017).
bladder cancer (5 papers, 2012 to 2023). "In fact, DPD deficiency in bladder cancer cells has been associated with gemcitabine sensitivity, whereas the overexpression of DPYD (DPD-coding gene) was linked to gemcitabine resistance via its catalytic inactivation." (PMID 36901917, 2023). "Recently, it has been shown that 5-fluorouracil (5-FU) with a strong dihydropyrimidine dehydrogenase (DPD) inhibitor elicits a significant response in bladder cancer with a high level of DPD." (PMID 25218240, 2014).
colorectal tumors (5 papers, 1998 to 2022). "RRM2 and UMPS upregulations and DPYD downregulation in colorectal tumors comply with the previous study." (PMID 27733154, 2016). "The observed overexpression of several 5-FU activating genes and DPYD downregulation deduce that chemotherapy naïve colorectal tumors share favorable gene expression profile for 5-FU therapy." (PMID 27733154, 2016). "On the basis of our gene expression data we may generalize, that colorectal tumors irrespective of the stage and localization share common downregulation of DPYD and upregulation of PPAT, UMPS, RRM2, and SLC29A1 transcripts." (PMID 27733154, 2016).
autism (4 papers, 2012 to 2023). Persistent deficits in social interaction and communication and interaction as well as a markedly restricted repertoire of activity and interest as well as repetitive patterns of behavior. "Examples include conditions such as Succinic Semialdehyde Dehydrogenase Deficiency (#271980), Autosomal Dominant Mental Retardation 21 (#615502), and Dihydropyrimidine Dehydrogenase Deficiency (#274270) to name just a few that are likely worthy of more intensive study in relation to autism." (PMID 26985359, 2016). "All partial and whole deletions, as well as the DPYD duplications were described to result in a similar phenotype which included intellectual disability, autism-like symptoms, speech delays, and often seizures and obesity." (PMID 36661700, 2023).
epilepsy (4 papers, 2015 to 2025). A brain disorder characterized by episodes of abnormally increased neuronal discharge resulting in transient episodes of sensory or motor neurological dysfunction, or psychic dysfunction. "From the current study, four variants were located in the epilepsy-related genes, the DPYD gene, NF1 gene, and WDR26 gene." (PMID 34055682, 2021). "These microdeletions affected 158 protein-coding RefSeq genes and exhibited an enrichment of genes previously associated with epilepsy (NRXN1, RBFOX1, PCDH7, KCNA2, EPM2A, RORB, PLCB1) and neuropsychiatric disorders (DPYD, CADM2, PARK2, GRM8, TSNARE1, TPH2, MACROD2)." (PMID 25950944, 2015).
Hyperammonemia (3 papers, 2016 to 2024). An increased concentration of ammonia in the blood. "At the onset of hyperammonemia, laboratory tests revealed high dihydropyrimidine dehydrogenase (DPD) activity and rapid 5-FU clearance." (PMID 27195162, 2016). "Stage 1 focused on the 43 hyperammonemia genes plus the DPYD gene." (PMID 30977266, 2019).
Intellectual disability (3 papers, 2017 to 2023). "The pathogenic homozygous or compound heterozygous variants within the DPYD gene are associated with dihydropyrimidine dehydrogenase (DPD) deficiency, and DPD-deficient infants may develop intellectual disability, motor retardation, and seizures." (PMID 34055682, 2021). "Other heterozygous microdeletions of 1p21.3 which contains the whole DPYD gene, as well as MIR137, have been associated with intellectual disability and autistic spectrum disorder." (PMID 36661700, 2023). "Deletion of the DPYD gene, whole or in part, results in loss of DPD enzyme activity which has been associated with intellectual disability, seizures and delayed motor skill development linked to congenital thymine-uraciluria." (PMID 36661700, 2023). "The disrupted coding sequences, altered expression, and association with congenital disease make it likely that the disruptions of FOXP1 and possibly DPYD contributed to the developmental delay and intellectual disability of the patient." (PMID 28126037, 2017). "For example, the disrupted FOXP1 and DPYD genes are known MCA/MR genes that may have contributed to the intellectual disability and developmental delay in our patient." (PMID 28126037, 2017).
metastatic disease (3 papers, 2008 to 2020). "A recent study reported frequent somatic DPYD mutations in SKCM and its upregulation in metastatic tumour." (PMID 33202946, 2020).
steatosis (3 papers, 2015 to 2022). Increased lipid within the cytoplasm of cells. "Predisposition to the development of steatosis may be associated with individual patient expression of genes involved in 5-FU metabolism, such as low level of dihydropyrimidine dehydrogenase (DPD) mRNA expression." (PMID 26273591, 2015). "In an in vitro model of fatty acid-induced steatosis, the pharmacologic inhibition of DPYD resulted in protection from lipid accumulation." (PMID 35982095, 2022). "Finally, it has been proposed that the onset of steatosis in patients treated with 5-FU could be attributed to the individual expression pattern of specific genes linked with 5-FU metabolism, in particular to decreased levels of dihydropyrimidine dehydrogenase (DPD)." (PMID 35052872, 2022). "However, it is possible that pharmacologic perturbation of DPYD activity may be a promising therapeutic strategy for the amelioration of steatosis and the prevention of NASH." (PMID 35982095, 2022). "These human in vitro models of hepatic steatosis highlight how DPYD enzymatic activity significantly contributes to lipid homeostasis and demonstrate how pharmacologic inhibition of DPYD may be a potential treatment option for the mitigation of diet-induced microvesicular steatosis." (PMID 35982095, 2022).
Thrombocytopenia (3 papers, 2015 to 2023). A reduction in the number of circulating thrombocytes. "The identification of A551 T in a patient experiencing grade 4 neutropaenia and thrombocytopaenia adds further support to the view that all rare DPYD variants that cause DPYD Deficiency Syndrome greatly increase the risk of 5-FU toxicity in heterozygotes." (PMID 24647007, 2015).
developmental delay (2 papers, 2017 to 2025). "A homozygous splice-site variant in DPYD was identified in a male patient with microcephaly, severe developmental delay, hypotonia, seizures, and ASD, potentially leading to toxic metabolite accumulation." (PMID 40558542, 2025).
glioblastoma (2 papers, 2017 to 2023). The most malignant astrocytic tumor (WHO grade IV).
mental disorder (2 papers, 2018 to 2023). A disease that has its basis in the disruption of mental process. "Located in this genomic region, miR-137 and (dihydropyrimidine dehydrogenase (DPYD) have both been previously associated with SZ and neurological and psychiatric disorders." (PMID 29751665, 2018).
microcephaly (2 papers, 2014 to 2025). A congenital or acquired developmental disorder in which the circumference of the head is smaller than normal for the person's age and sex. "Variants in TMEM132E (rs4795954, MAF 13.2%) and in DPYD (rs2297595, MAF 6.1%) are common, and neither has been associated with brain development or microcephaly." (PMID 23692340, 2014).
alopecia (1 paper, 2020). Hair loss usually from the scalp. "The profile of toxicities of FOLFOX and FOLFIRI regimens was different in some adverse reactions such as peripheral neuropathy and alopecia and we did not observe any relationship between adverse reactions and DPYD polymorphism." (PMID 32546132, 2020).
Alzheimer disease (1 paper, 2026). A progressive, neurodegenerative disease characterized by loss of function and death of nerve cells in several areas of the brain leading to loss of cognitive function such as memory and language. "Subcluster 2 expressed high levels of white matter associated genes (NRP1, MERTK, and NCKAP5) while subcluster 3 displayed a disease‐associated signature (STARD13, MITF, GPNMB, and DPYD) previously observed in Alzheimer's disease (AD) and Multiple Sclerosis (MS)." (PMID 41283828, 2026).
anemia (1 paper, 2020). A reduction in the number of red blood cells, the amount of hemoglobin, and/or the volume of packed red blood cells. "The most commonly experienced grade 3 or grade 4 toxicity in both DPYD wild-type and mutant patients was anemia in hematological and vomiting in gastrointestinal toxicity." (PMID 33280607, 2020).
autonomic dysfunction (1 paper, 2023). "This raises the possibility that DPYD variants may be a predisposing factor for autonomic dysfunction." (PMID 40217298, 2023).
diabetes (1 paper, 2021). "Of the top 15 proteins found by Cytoscape 3.6.1, 8, CAT and OGG1 (downregulated) and CASP3, COMT, CYP1B1, DPYD, NQO1, and PTGS1 (upregulated), were dysregulated in diabetes-related kidney disease." (PMID 34367469, 2021).
glioma (1 paper, 2023). A benign or malignant brain and spinal cord tumor that arises from glial cells (astrocytes, oligodendrocytes, ependymal cells). "Significantly lower thymidylate synthase (TS) and dihydropyrimidine dehydrogenase (DPD) expressions in hG008, GL261 and TSG than in other glioma cells were confirmed by quantitative reverse transcription PCR." (PMID 37693056, 2023).
head and neck cancer (1 paper, 1999). A primary or metastatic malignant neoplasm affecting the head and neck.
Hepatic steatosis (1 paper, 2022). Steatosis is a term used to denote lipid accumulation within hepatocytes. "As the conclusions drawn from this body of work were based on data collected from human in vitro cell model systems, a future effort should be dedicated to assessing the functional effects of DPYD inhibition in a rodent model of hepatic steatosis." (PMID 35982095, 2022). "The studies presented herein describe a novel role for DPYD in hepatocyte metabolic regulation as a modulator of hepatic steatosis." (PMID 35982095, 2022). "However, a body of preclinical work demonstrates uridine levels influence hepatic lipid accumulation, providing scientific rationale for DPYD inhibition as a significant driver of liver lipid levels and a potential clinical target for mitigating hepatic steatosis." (PMID 35982095, 2022). "Since the DPYD inhibitor, Gimeracil, is already deemed safe and tolerable in the clinic when delivered in combination with the chemotherapeutic 5-FU for the treatment of various cancers, Gimeracil may be a promising therapeutic for the alleviation of hepatic steatosis." (PMID 35982095, 2022).
homocystinuria (1 paper, 2023). An autosomal recessive inherited metabolic disorder caused by mutations in the CBS, MTHFR, MTR, and MTRR genes. "Moreover, the study identified three patients with compound heterozygous CBS mutations causing homocystinurias, compound heterozygous DPYD mutations causing DPD deficiency, and homozygous GALC mutations causing Krabbe Disease, respectively." (PMID 37237429, 2023).
leukopenia (1 paper, 2024). "The occurrence of leukopenia symptoms in the two first FAC chemotherapy cycles (early leukopenia) was determined by DPYD rs291583 variant GG (OR 2.25; 1.25–4.05; p = 0.006) and AKR1C3 rs3209896 genotypes AA and GG (OR 1.77; 1.08–2.89; p = 0.021)." (PMID 39596349, 2024). "In multivariate analysis risk, symptoms of overall leukopenia were conditioned by two genetic factors: ABCC1 gene rs129081 allele G (OR 1.89; 0.27–0.99; p = 0.048) and DPYD rs291593 allele T (OR 1.73; 1.08–2.76; p = 0.020)." (PMID 39596349, 2024).
liver fibrosis (1 paper, 2025). "The protection against liver fibrosis conferred by the hydroxysteroid, 17-beta dehydrogenase 13 (HSD17B13), is associated with reduced dihydropyrimidine dehydrogenase-mediated pyrimidine catabolism." (PMID 39917615, 2025).
lung disease (1 paper, 2020). "Studies of genotype-phenotype correlation related to DPYD are limited, but results have demonstrated that DPYD is required for the epithelial-to-mesenchymal transition, suggesting involvement in lung disease via pulmonary fibrosis." (PMID 32127447, 2020).
Optic neuropathy (1 paper, 2024). "In addition to these patients with possible inherited optic neuropathies, six other patients (20.0% of patients with an alteration of the GCC) carried suspected unique pathogenic variants in six recessive genes (DPYD, AGXT, CYP1B1, ACO2, LTBP2 and FDXR)." (PMID 38796496, 2024). "The susceptibility variants identified in the other six patients were not firmly responsible on their own for a genetic form of optic neuropathy since they were found in recessives genes (DPYD, ACO2, AGXT, CYP1B1, LTBP2 and FDXR) with a single affected allele." (PMID 38796496, 2024).
Oral Squamous Cell Carcinoma (1 paper, 2019). "The study aims to analyze Thymidylate Synthase (TS) and Dihydropyrimidine Dehydrogenase (DPD) Expressions on 5-Fluorouracil in Oral Squamous Cell Carcinoma (OSCC)." (PMID 30803213, 2019). "Evaluation of characteristics of thymidylate synthase (TS) and dihydropyrimidine dehydrogenase (DPD) on 5-Fluorouracil in oral squamous cell carcinoma would help the clinicians and researchers to develop new anti-cancer techniques that can be effective dealing with malignancies." (PMID 30803213, 2019).